METTL16 (methyltransferase 16, RNA N6-adenosine)
Diseases named in the same sentence as METTL16 in open-access papers (continued):
Sharing a sentence is not in itself a finding about the gene and the disease.
bladder cancer (continued). "Collectively, METTL16 regulates BLCA growth and chemotherapy response in an m6A-dependent manner through the HIF-2α–METTL16–PMEPA1–autophagy axis, providing novel mechanistic insights and potential therapeutic strategies for bladder cancer." (PMID 41322419, 2025). "METTL16, by binding to the m6A site of the 3' end of prostate transmembrane protein androgen-induced protein 1 (PMEPA1), reduces its mRNA stability, thus inhibiting the proliferation of bladder cancer cells and increasing sensitivity to cisplatin, mediated by the autophagy pathway." (PMID 39155349, 2024). "In addition, METTL16 reduced the mRNA stability of prostate transmembrane protein androgen induced-1 (PMEPA1) via binding to its m6A site in the 3'-UTR, thereby inhibited the proliferation of bladder cancer cells and increased the sensitivity of cisplatin through PMEPA1-mediated autophagy pathway." (PMID 38385084, 2024).
cholangiocarcinoma (6 papers, 2023 to 2025). A carcinoma that arises from the intrahepatic biliary tree (intrahepatic cholangiocarcinoma) or from the junction, or adjacent to the junction, of the right and left hepatic ducts (hilar cholangiocarcinoma). "In cholangiocarcinoma (CCA), METTL16 targets PRDM15 to regulate FGFR4 expression, promoting cell proliferation and malignant progression." (PMID 41256854, 2025). "Our analyses indicate that METTL16 is upregulated in CCA tissues when compared to matched or unmatched non-tumorous tissues in TCGA-Cholangiocarcinoma (TCGA-CHOL) and GSE107943 datasets." (PMID 37817227, 2023).
leukemia (6 papers, 2022 to 2025). A malignant (clonal) hematologic disorder, involving hematopoietic stem cells and characterized by the presence of primitive or atypical myeloid or lymphoid cells in the bone marrow and the blood. "Although accumulating evidence suggests that the m6A writer METTL16 is involved in leukemia, the molecular pathway(s) by which it contributes to leukemogenesis remain unexplored." (PMID 40946103, 2025). "Additionally, Mettl16 was shown to have a significant role in leukemia stem cells and leukemia initiating self-renewal." (PMID 38028538, 2023). "In summary, METTL16 drives AML progression and leukemia stem cell maintenance through m6A-dependent modulation of metabolic and transcriptional pathways, establishing it as a key epitranscriptomic regulator and a promising therapeutic target in AML." (PMID 41322419, 2025). "Studies have shown that METTL16 is aberrantly overexpressed in human AML cells, with enrichment in leukemia stem cells (LSCs) and leukemia-initiating cells (LICs)." (PMID 41322419, 2025).
liver cancer (6 papers, 2021 to 2024). An epithelial or non-epithelial malignant neoplasm that arises from the liver. "We believe that the difference of prognostic significance of METTL16 between GC and liver cancer is due to the fact that the same gene encoding the methyltransferase plays different roles in different cancers." (PMID 34075693, 2021). "We demonstrated that the knockdown of METTL16 accelerated the invasion and migration of liver cancer cells." (PMID 39101773, 2024). "Vice versa, overexpression of METTL16 significantly suppressed the invasion and migration of liver cancer cells." (PMID 39101773, 2024). "For example, METTL16 enhances mRNA translation efficiency, thereby influencing the self-renewal of hepatic cancer stem cells and impacting the development of liver cancer." (PMID 39155349, 2024). "For example, METTL16 expression promotes the progression of diverse cancer types, including lung, breast, stomach, and liver cancers." (PMID 39101773, 2024). "In contrast, increased METTL16 expression predicts a longer survival in individuals with liver cancer." (PMID 36091006, 2022). "Next, we investigated whether METTL16 expression affected the phenotype of liver cancer cells." (PMID 39101773, 2024). "METTL16 has been reported to have a function independent of m6A in liver cancer cells in vitro; nevertheless, it is unclear whether METTL16 plays an m6A-dependent or m6A-independent role in vivo." (PMID 38605226, 2024).
cervical cancer (5 papers, 2022 to 2024). A primary or metastatic malignant neoplasm involving the cervix. "In human cervical cancer tissues, the expression of PD-L1, METTL16, ZC3H13, and YTHDF1 was highly expressed in cervical cancer patients compared with surrounding normal tissues." (PMID 36091006, 2022). "METTL16 reduces the stability of PD-L1 mRNA via its m6A modification, consequently increasing the number of tumor-infiltrating immune cells in the immune microenvironment of cervical cancer, such as plasma cells and regulatory T cells." (PMID 39155349, 2024). "Three m6A regulators (METTL16, YTHDF1, and ZC3H13) were chosen as the minimum standard for constructing a predictive signature, and the riskscore of each cervical cancer patient was determined." (PMID 36091006, 2022). "Differential analysis results showed that many m6A-related genes were differentially expressed between cervical cancer tissues and normal tissues, including METTL14, METTL16, ZC3H13, YTHDC1, and YTHDC2." (PMID 36058934, 2022). "To explore the contribution of METTL16 to colorectal carcinogenesis, we utilized short‐hairpin RNA (shRNA)‐mediated knockdown to silence METTL16 expression in HCT116 (CRC cell line), SW620 (CRC cell line) and HeLa cells (cervical cancer cell line)." (PMID 38084791, 2024). "Moreover, downregulation of METTL16, YTHDF1, or ZC3H13 in two cervical cancer cell lines elevated the expression of PD-L1." (PMID 36091006, 2022). "Furthermore, this study created a three-gene prognostic marker consisting of an m6A methylation regulatory factor, namely, METTL16, YTHDF1, and ZC3H13, and the calculated riskscore had a good predictive effect on cervical cancer patients." (PMID 36091006, 2022). "This study indicated that METTL16, YTHDF1, and ZC3H13 could regulate the expression of PD-L1 in cervical cancer." (PMID 36091006, 2022). "However, the relevance of METTL16 and ZC3H13 in cervical cancer is still not fully known." (PMID 36091006, 2022).
pancreatic cancer (5 papers, 2021 to 2025). "This study aims to build upon the current understanding by focusing on the unexplored role of METTL16 in pancreatic cancer." (PMID 39434688, 2024). "METTL16 and METTL3 were identified as key m6A regulators associated with improved prognosis in pancreatic cancer patients (P<0.05)." (PMID 39434688, 2024). "In conclusion, this study uncovers a novel regulatory pathway in pancreatic cancer involving METTL16, MROH8, TBP, and m6A modifications." (PMID 39434688, 2024). "To further explore the impact of m6A genes on pancreatic cancer prognosis, we conducted transcriptomic analyses and identified METTL3 and METTL16 as the key m6A ‘writer’ genes associated with better patient outcomes." (PMID 39434688, 2024). "A recent study has shown that METTL16 expression in pancreatic cancers confers synthetic lethality to PARP inhibition, revealing a novel function of METTL16 in homologous recombination repair, which is important for maintaining genome stability." (PMID 39101773, 2024). "Functional assays, including METTL16 knockdown and overexpression experiments, were conducted in pancreatic cancer cell lines, patient-derived organoids, and animal models." (PMID 39434688, 2024). "This study addresses these gaps by investigating the role of m6A modifications, especially the m6A writer gene METTL16, in regulating pancreatic cancer metastasis." (PMID 39434688, 2024). "Our study found that METTL16 suppresses pancreatic cancer progression by downregulating CAPN2 via m6A-mediated regulation." (PMID 39434688, 2024). "Regarding pancreatic cancer, studies have confirmed that METTL16 was downregulated and played a prognostic role for pancreatic cancer patients." (PMID 37859814, 2023). "From the GEO databases GSE15471 and GSE16515, it was found that the METTL16 mRNA levels are downregulated in pancreatic cancer (GSE15471, p = 0.0202 and GSE16515, p = 0.0007)." (PMID 37859814, 2023). "Our group recently revealed that METTL16 was significantly downregulated in pancreatic cancer and low METTL16 expression was a poor prognostic factor." (PMID 34239358, 2021). "The results again indicated that METTL16 is downregulated in pancreatic cancer tissues." (PMID 37859814, 2023). "Furthermore, our group found that METTL16 was significantly decreased in pancreatic cancer and was correlated with patient survival, indicating the prognostic value of METTL16 in pancreatic cancer." (PMID 34239358, 2021). "In addition, METTL16 inhibited the p21 pathway by mediating m6A modification, resulting in a tumor-suppressive role in the proliferation of pancreatic cancer cells." (PMID 34239358, 2021). "This study reveals a novel regulatory axis involving METTL16, MROH8, and TBP that modulates CAPN2 expression, contributing to the suppression of pancreatic cancer progression." (PMID 39434688, 2024). "This study thus proposes a novel regulatory axis involving METTL16, MROH8, and CAPN2, expanding our understanding of how m6A modifications influence pancreatic cancer progression and offering potential new therapeutic targets." (PMID 39434688, 2024). "Therefore, METTL16 may be a new therapeutic target for pancreatic cancer." (PMID 34239358, 2021). "Furthermore, METTL16 and METTL3 are recognized as pivotal m6A modulators correlated with favorable prognosis in pancreatic cancer patients." (PMID 40986143, 2025). "Specifically, METTL16 and METTL3 have distinct prognostic implications in pancreatic cancer." (PMID 40986143, 2025). "Subsequent experiments confirmed this hypothesis; we found that METTL16 inhibits CAPN2 expression by regulating MROH8, which in turn affects the progression and metastasis of pancreatic cancer." (PMID 39434688, 2024). "Additionally, our METTL16 RIP-qPCR data demonstrated strong binding between METTL16 protein and MROH8 transcripts in pancreatic cancer cells." (PMID 39434688, 2024).
Epithelial Ovarian Cancer (4 papers, 2023 to 2025). "Studies have shown that METTL16 is significantly downregulated in epithelial ovarian cancer (EOC) tissues and cells, whereas its target lncRNA MALAT1 is highly expressed, exhibiting a negative correlation." (PMID 41322419, 2025). "In summary, METTL16 acts as a key regulator of OV progression through modulation of MALAT1 and β-catenin signaling, and targeting the METTL16–MAT2A axis may represent a promising therapeutic strategy for ovarian cancer." (PMID 41322419, 2025).
lung adenocarcinoma (4 papers, 2023 to 2025). A carcinoma that arises from the lung and is characterized by the presence of malignant glandular epithelial cells. "Notably, elevated METTL16 expression was associated with poorer overall survival and progression-free intervals in lung adenocarcinoma (LUAD)." (PMID 40885716, 2025).
pancreatic adenocarcinoma (4 papers, 2023 to 2025). "The aim of this study was to investigate the mechanism of METTL16, which mediates m6A modification, and its role in pancreatic adenocarcinoma (PDAC) cell proliferation." (PMID 37182151, 2023).
pancreatic ductal adenocarcinoma (3 papers, 2024 to 2026). An infiltrating adenocarcinoma that arises from the epithelial cells of the pancreas. "This phosphorylation-dependent regulatory mechanism underscores METTL16's dual role in maintaining genome stability and its potential as a therapeutic target in HR repair-deficient cancers, including pancreatic ductal adenocarcinoma." (PMID 41459114, 2026). "Furthermore, in pancreatic ductal adenocarcinoma and gastric adenocarcinoma, METTL16 expression is significantly associated with tumor-infiltrating immune cells such as B cells and CD8+ T cells." (PMID 41459114, 2026). "In pancreatic ductal adenocarcinoma, METTL16 phosphorylation plays a critical role in DNA damage repair, particularly in homologous recombination repair." (PMID 41459114, 2026). "Conversely, lower METTL16 expression is observed in pancreatic ductal adenocarcinoma, endometrial cancer, epithelial ovarian cancer, papillary thyroid carcinoma, and urothelial carcinoma, which are associated with poor prognosis." (PMID 41459114, 2026). "METTL16 activates the p21 signalling pathway by m6A modification and inhibits the proliferation of pancreatic ductal adenocarcinoma cells." (PMID 39289775, 2024). "The down-regulation of METTL16 leads to a concomitant increase in DVL2 levels, thereby promoting the progression of pancreatic ductal adenocarcinoma." (PMID 41459114, 2026). "In addition, METTL16 can inhibit the translation of DVL2 mRNA through m6A modification, thereby regulating the Wnt/β-catenin signalling pathway and inhibiting the proliferation of pancreatic ductal adenocarcinoma cells." (PMID 39289775, 2024).
papillary thyroid cancer (3 papers, 2024 to 2026). "In papillary thyroid carcinoma, DNA hypermethylation mediated by DNA methyltransferase 1 (DNMT1) in the promoter region of METTL16 leads to reduced transcription and expression of METTL16." (PMID 41459114, 2026).
bladder tumors (2 papers, 2021 to 2024). "This study confirmed that METTL16 was positively correlated with the level of m6A in bladder tumor cell line T24 and UMUC3 through dot blot." (PMID 38385084, 2024). "Furthermore, interfering with PMEPA1 after knocking down METTL16 inhibited proliferation of bladder tumor cells, while increased the rate of cisplatin-induction apoptosis, the sensitivity of cells to cisplatin and the expression of apoptosis related protein." (PMID 38385084, 2024). "It was further confirmed that knockdown of METTL16 could promote proliferation and reduce the sensitivity to cisplatin chemotherapy of bladder tumor cell T24 to a certain extent in vivo." (PMID 38385084, 2024). "Similarly, in vivo experiments also showed that knockdown of METTL16 in T24 cell led to the development of smaller tumors and reduce the sensitivity of bladder tumor to cisplatin chemotherapy in nude mice compared with the control group." (PMID 38385084, 2024). "This indicates that METTL16 may have the potential to be a prognostic indicator for bladder tumors." (PMID 38385084, 2024). "However, some m6A regulators, including METTL3, RBM15B, YTHDF1, YTHDF2, and IGFBP3, were significantly overexpressed in bladder tumors, and some m6A regulators, including METTL14, METTL16, ZC3H13, and YTHDF3, were markedly downregulated in bladder tumors." (PMID 35004726, 2021).
esophageal cancer (2 papers, 2025 to 2026). A primary or metastatic malignant neoplasm involving the esophagus. "In esophageal cancer, METTL16 expression is positively correlated with clinical stage, with higher levels observed in patients at more advanced stages, suggesting its involvement in esophageal cancer progression, particularly in later stages." (PMID 41459114, 2026).
HbH disease (2 papers, 2024 to 2025). "Therefore, this article explored the role of methyltransferase like 16 (METTL16) in HbH disease." (PMID 39088431, 2024). "This study also found that METTL16 and SLC5A3 mRNA were down-regulated in HbH-CS disease patients compared with other types of HbH disease patients (—SEA/ αWS α,—SEA/- α3.7,—SEA/- α4.2)." (PMID 39088431, 2024). "The downregulation of METTL16 and SLC5A3 mRNA in HbH disease patients may be a compensatory response, which can reduce the elevated ROS caused by iron deposition and oxidative stress." (PMID 39088431, 2024). "This study revealed the downregulation of METTL16 and YTHDF3 in patients with HbH disease, possibly due to the compensatory response of the body to reduce the aggregation of HbH inclusion bodies on the red blood cell membrane, which leads to a decrease in the plasticity of red blood cells." (PMID 39088431, 2024). "We can also develop drugs for the METTL16_ YTHDF3_ SLC5A3 pathway, such as agents designed to regulate METTL16 to reduce ROS and change the expression of IGF2BP3 to improve haemoglobin, which will provide a new direction for the treatment of HbH disease." (PMID 39088431, 2024). "Moreover, METTL16 possibly affects the expression of haemoglobin through IGF2BP3, which regulates the clinical phenotype of HbH disease." (PMID 39088431, 2024).
Hepatic steatosis (2 papers, 2022 to 2026). Steatosis is a term used to denote lipid accumulation within hepatocytes. "Knockdown of METTL16 alleviated hepatic steatosis, insulin resistance, and fibrosis in high-fat diet-fed mice." (PMID 41952207, 2026). "Mechanistically, cell death-inducing DFF45-like effector family members A (CIDEA) was identified as a downstream mediator of METTL16-driven hepatic steatosis." (PMID 41952207, 2026). "CONCLUSION: METTL16 promotes hepatic steatosis and immune-mediated fibrogenesis in MASLD." (PMID 41952207, 2026). "Immunohistochemistry analysis of METTL16 displayed that positive particles were diffusely distributed in the cytoplasm of hepatocytes in HFD mice, further confirming that the expression levels of METTL16 were significantly elevated in the development of hepatic steatosis." (PMID 36518278, 2022).
liver fibrosis (2 papers, 2022 to 2023). "Furthermore, mechanism studies showed that METTL16 upregulated the expression level of lipogenic genes CIDEA in HepG2 cells; otherwise, METTL16 also plays vital role in liver fibrosis." (PMID 38045858, 2023).
lymph node metastases (2 papers, 2023 to 2024). "Specifically, increased METTL16 expression was associated with recurrence, advanced clinical stage and lymph node metastases." (PMID 38084791, 2024). "The outcomes showed that the low-expression level of METTL16 was obviously linked with poor prognostic factors, such as FIGO stage, tumor size, and lymph node metastasis." (PMID 37927399, 2023).
male infertility (2 papers, 2024 to 2025). The inability of the male to effect fertilization of an ovum after a specified period of unprotected intercourse. "METTL16 deficiency in male germ cells causes a reduction in differentiated spermatogonia and compromised DNA replication before entering the meiotic prophase, which ultimately lead to male infertility." (PMID 39030605, 2024). "The deletion of either Mettl16 or Ythdc1 with Stra8‐Cre disrupted the gene expression related to chromosome organisation and segregation, resulting in aberrant differentiation of spermatogonia and male infertility." (PMID 39614650, 2025). "In addition, germ cell-specific knockout of mouse Mettl16 generated by Vasa-Cre (induces recombination in germ cells as early as embryonic day 15) exhibited male infertility with atrophied testes." (PMID 39030605, 2024).